IL1B (interleukin 1 beta)
Diseases named in the same sentence as IL1B in open-access papers (continued):
Sharing a sentence is not in itself a finding about the gene and the disease.
infection (continued). "The inflammatory response, often activated as a result of infection, injury, or stress, leads to the release of pro-inflammatory cytokines, such as interleukin-6, tumor necrosis factor-alpha, and interleukin-1 beta." (PMID 39355377, 2024). "In order to define the time course of gene expression for IL-1β and IL-6, RNA analysis was performed at 24 h, 48 h and one week after infection with the highest bacterial concentration." (PMID 38399810, 2024). "E2 treatment post-infection significantly decreased the mRNA expression of inflammatory genes IL-1β, IL8, IL6 and TNF-α compared to the E. coli infected group (P < 0.05)." (PMID 39600797, 2024). "IL-1β is essential in the early stages of infection, where it drives inflammation, recruits immune cells like neutrophils and monocytes, and aids in pathogen clearance." (PMID 39362931, 2024). "A comparison of the day 20 post-infection group with the healthy control group and the day 10 post-infection group revealed that the IL-1β mRNA levels of the day 20 post-infection group exhibited an average 19.8-fold increase (p < 0.005)." (PMID 39766497, 2024). "The increased mouse serum IL-6 and IL-1β production was in a similar line with the increased IL-6 or IL-1β cytokine generation in EX-527 or 3TYP treated peritoneal macrophages under the infection scenario." (PMID 39693143, 2024). "The infection of macaques with HTLV-1WT or HTLV-1p12KO was associated with higher plasma levels of IL-10 after 21 weeks, while IL-6, IFN-γ, IL-18, and IL-1β were only elevated in animals infected with HTLV-1WT." (PMID 38668247, 2024). "In this study, we cultured bone-derived chicken dendritic cells (ck-BM-DC) and examined gene expression levels of IFN-α, TLR-3, TLR-7, MHC-I, IL-1β, IL-6, Mx, Casp-3, and Casp-8 pre/post infection with AIV." (PMID 39281683, 2024). "Our results show a significant decrease in IL-1β (p = 0.004), IL-8 (p = 0.01), IL-12 (p < 0.0001), and IFNγ (p = 0.006) at 5 days post infection in the presence of 0.5% Aq." (PMID 38790647, 2024). "This points to a potential interaction of the MCMV vRIA with the cZBP1 to reduce IL-1β released during infection." (PMID 37012234, 2023). "Inflammasome activation and secretion of IL-1β/IL-18 following infection with M. ulcerans strain Agy99, M. marinum, or M. pseudoshottsii were also completely abolished in ASC-deficient macrophages." (PMID 37910490, 2023). "qPCR and Multiplex immunoassay performed in lung homogenates confirmed that, in line with cytospin analysis, infection at ZT12 was associated with lower levels of expression of pro-inflammatory cytokines TNFα, IL-6, and IL-1β and the chemokine CXCL1." (PMID 36896128, 2023). "aureus, Δlgt S. aureus induced low levels of PGE2, IL-1β, IL-6, IL-10, and IL-8 secretion into neutrophil supernatants after infection of neutrophils for 9 h at MOI 3:1 and MOI 10:1 (P < 0.01, P < 0.001)." (PMID 37168122, 2023). "A single pig from the Ad-HA/NP+Ad-IL-1β group showed inappetence and cough between 1 to 3 days post-infection (DPI)." (PMID 37153548, 2023). "(B) Correlation between PTX3 and IL-1β protein levels in lung homogenates of all infected mice sacrificed from 2 to 48 hr post-infection (data pooled from five independent experiments, n = 60); Pearson correlation coefficient is reported." (PMID 37222419, 2023). "Infection boosted IL-1β, IL6 and NLRP3 levels in TLR7 expressing AMФ but these proinflammatory markers were suppressed upon TLR7 deficiency." (PMID 37795093, 2023). "Ad-HA/NP+Ad-IL-1β administration also significantly increased pH1N1-specific IgG titers in nasal swabs (1:576) reaching the titers measured after pH1N1 infection (1:560), which were significantly higher compared to titers in controls." (PMID 37153548, 2023). "Compared to cells cultured with DMSO, GFs cultured in the presence of DAC released at least 10-fold higher amounts CCL20 upon infection with P. gingivalis or stimulation with TNF or IL-1β." (PMID 36776856, 2023).
infection (continued). "Infection with NTHi is also associated with transcriptional upregulation of cytokines CCL2 (MCP1), TNF, IL-1β, IL-6, CXCL8 and alarmins (TSLP, IL-33 and IL-25)." (PMID 37180449, 2023). "At day 3 post-infection, young and aged neutrophils expressed similar levels of Il1b, but young neutrophils expressed higher levels of Il1a; the chemokines Ccl3, Cxcl3, and Cxcl1; and Cd274 (encodes PD-L1)." (PMID 37852965, 2023). "Several DEGs specific to cytokines Cxcl1, Cxcl2, Ccl3, and Il1b were upregulated in bone-marrow-derived macrophages at both 1 and 24 h post-infection with Bb validating the mRNA abundance observed in scRNA-Seq analysis of infected splenocytes." (PMID 38149246, 2023). "Then, we tested the effect of OLE in CFBE cells co-treated with LPS from P. aeruginosa or IL-1β/TNFα for 4 h to mimic the infection or inflammatory milieu of CF airways." (PMID 37443798, 2023). "Changes in gene transcription in the blood were minimal; there was a significant decrease in Il1b (IL-1β) transcription when comparing the B/I to the Infection condition at 12 h." (PMID 37929965, 2023). "The MAB-R variant triggered higher levels of IL-1β compared to the S variant, and treatment with cysteamine and cystamine drastically reduced IL-1β in the PBMC model of infection." (PMID 36674717, 2023). "Analysis of IL-1β transcript expression demonstrated significance for the interaction of infection status with primary Müller isolate (p < 0.001), and infection with Mon601 was the factor that most strongly influenced IL-1β expression." (PMID 37515098, 2023). "IL-1β is a potent pro-inflammatory cytokine, which is produced and released at the early stages of infections, stressful situations or lesions." (PMID 36680273, 2023). "IL-1β is an important pro-inflammatory factor that plays a major role in cellular anti-infection processes." (PMID 36926518, 2023). "IL-1β is a pro-inflammatory cytokine produced by various immune cells in response to infection and injury in order to provide resistance to pathogens." (PMID 37781285, 2023). "IL-1β measurements showed the most significant readings from dual-species infection compared to uninfected controls (***P<0.001)." (PMID 36748431, 2023). "TNF-α, IL-6, and IL-1β are primary cytokines generated by activated macrophages during initial inflammatory responses of host defense and infection, consistent with previous reports." (PMID 38015971, 2023). "The accumulated secretion of IL-1β was additionally suppressed after infection with type 2 (p < 0.05)." (PMID 37099541, 2023). "After Vibrio alginolyticus (V. alginolyticus) infection, intraperitoneal injection of recombinant IL-1β improved the survival rate of large yellow croaker (Larimichthys crocea) and reduced the tissue bacterial load." (PMID 36809593, 2023). "In this regard, Wan and colleagues indicated that ERK/AP‐1 signaling pathway increases the transcription of pro‐IL‐1β to facilitate the activation of NLRP3 inflammasome upon IV infection." (PMID 37773712, 2023). "ASMase is considered to have a protective role during infection, based on the studies on ASMase knockout mice, which had exaggerated IL-1β release and increased mortality when infected with Pseudomonas aeruginosa." (PMID 37175979, 2023). "COs and BVOs also expressed IL1β and TNFα after infection, but the expression levels were lower than fCBOs." (PMID 36697403, 2023). "They showed that ZBP1 can modulate neutrophil influx and NET formation into the lung via managing necroptotic cell death and controlling NLRP3 activation and IL‐1β release during IV infection." (PMID 37773712, 2023). "IL-1β is the central mediator of inflammation and is crucial for the body’s defense against infection." (PMID 36838365, 2023). "Leukocytes play a fundamental role in the healing of injuries due to the anti-infection action and immunological regulation through the secretion of immune cytokines, such as interleukin (IL)-1β, IL-4 and IL-6, and tumor necrosis factor alpha (TNF-α)." (PMID 37330965, 2023).
infection (continued). "RSV induces the activation of the NLRP3 inflammasome and caspase 1, and both events are crucial for the secretion of IL-1β, IL-33, and IL-18 during infection." (PMID 37508374, 2023). "On the other hand, il-1β expression levels were higher in infected fish sampled at 3 and 6 h post infection than levels of control (PBS)." (PMID 37629124, 2023). "Studies show that host cells infected with C. trachomatis release pro-inflammatory cytokines throughout their growth cycle, which together with IL-1b, TNF, and IL-10, are associated with poorer prognosis of the infection." (PMID 36897879, 2023). "TNFα and IL1β play an important role in regulating innate immune systems against infection and other stress condition." (PMID 36977939, 2023). "We were surprised initially by the increased IL-1β response to infection by parental Y. pseudotuberculosis in comparison to infection by the MYM effectorless strain." (PMID 37621095, 2023). "Our results show a possible relationship between the IFI16 inflammasome and IL-1β secretion during infection with this strain; nevertheless, it is important to elucidate the participation of this inflammasome during ncp-BVDV replication." (PMID 37515181, 2023). "This recognition can lead to a secretion of pro-inflammatory cytokines like IL-1β and IL-6 as well as chemokines that attract phagocytic heterophils and macrophages to the site of infection as a response." (PMID 37261344, 2023). "We collected supernatants of mPEOs at 0, 2, 4, 8, and 24 h after USA300 infection and measured IL-1β expression levels of 0 ± 0, 982.00 ± 108.55, 2562.62 ± 172.03, 2621.46 ± 137.35 and 1315.83 ± 86.14 pg/mL respectively by ELISA." (PMID 36631452, 2023). "We next compared the inflammatory response initiated after BMDM infection and observed that, similarly to in vivo results, TNFα and IL1β production was lower in Tirap+/- and Tirap-/- macrophages compared to infected WT cells." (PMID 36888688, 2023). "In contrast, low-infected larvae show lower TNFα and IL1β responses and were able to control parasitaemia and recover from the infection." (PMID 36829432, 2023). "NLRP3 is the most characteristic inflammasome activated by the infection or stress reaction of cells, which is responsible for the maturation of pro-inflammatory cytokines IL-1β and IL-18." (PMID 36816025, 2023). "A growing body of evidence shows the relevance of neutrophil secreted IL-1β in immune responses against different pathogens, especially in murine models of infection." (PMID 38127952, 2023). "Gentamicin incites mitochondrial ETC complex dysfunction, and inflammation, releasing pro-inflammatory cytokines like IL-1β, a vital component of the host’s defense against infection and injury." (PMID 37521462, 2023). "Recent reports have shown that IL-1β secretion from LPS-primed macrophages is induced by both mycolactone treatment and infection with M. ulcerans." (PMID 37910490, 2023). "In the same report, ExoU was shown to reduce serum IL-1β and enhance bacterial fitness in a systemic model of infection in mice." (PMID 36611990, 2023). "TNF-mediated increase in Casp11 transcription can still be observed at 16 hours following priming (at the time of infection), while Il1a and Il1b transcription fades by that time." (PMID 37279255, 2023). "As we anticipated, several interleukins, including interleukin-1 beta (IL-1β) and interleukin-8 (IL-8), were induced after infection in this study." (PMID 36910190, 2023). "IL-1β is a pro-inflammatory biomarker that is secreted by macrophages in response to infection and serves to recruit neutrophils and other leukocytes." (PMID 37228436, 2023). "Cytokines such as IL-1β appeared secreted in higher amounts following infection with the knockout mutant strain, suggesting the possibility of a stronger inflammatory response." (PMID 37130958, 2023).
infection (continued). "A group of NLRs are associated with the formation of the inflammasome, a cytosolic multiprotein complex that, once activated, induces the production of IL-1β and IL-18 and the recruitment of immune cells to the site of infection." (PMID 37243291, 2023). "The concentration of IL-1β in the cell culture was measured by ELISA, and caspase-1 in PAMs was detected by western blotting 72 h after infection." (PMID 37256059, 2023). "NLRP3 expression and ASC and caspase‐1 are needed to cleave pro caspase‐1 to secrete mature IL‐1β following IV infection." (PMID 37773712, 2023). "Briefly, immune responses induced by HuN4 and SD53-1603 infections shared some similarities, such as the elevation and recovery of IL-1β, TNF-α, and IFN-γ levels." (PMID 37920268, 2023). "Since bacterial infection of the mesothelium is characterized by a production of pro-inflammatory cytokines and an influx of innate immune cells to the site of infection, we assessed the levels of pro-inflammatory cytokines TNFα, IL-1β, and MCP-1." (PMID 37237611, 2023). "Higher levels of IL-1β and IL-6 were detected in cultures sensitized prior to infection compared to unstimulated infected cells." (PMID 37841240, 2023). "Our study has shown that infection with the attenuated recombinant Del2R induced high levels of IL-1β and TNF-α production in PAMs compared with infection with ASFV-WT." (PMID 37566637, 2023). "We found that infection with E. coli mcr-1+ significantly decreased the secretion of pro-inflammatory cytokines IL-8, IL-1β, and TNF-α (p values, 0.002 to <0.0001)." (PMID 36670449, 2023). "In vitro, infection of murine peritoneal macrophages with a toxigenic strain of C. difficile results in the release of the proinflammatory cytokine pro-IL-1β, a process that is dependent on MyD88 and, to some extent, TLR2." (PMID 38133438, 2023). "RTS11 cells pre-treated with CgPACAP-38 and infected with F. psychrophilum produced a significant up-regulation of IL-1β at day 3 after infection, while IL-6 and TNF-α were up-regulated from day 1 post-infection." (PMID 37887185, 2023). "Immunoblot and ELISA analysis of BMDMs pretreated with CA followed by ∆yopM infection showed that pyrin remained phosphorylated on S205, and there was a significant decrease in IL-1β release." (PMID 37787552, 2023). "Among infection status (PI, HC and R), only IL-1β (p = 0.0384, t test), IL-12p40 (p = 0.0272, t test), and IL-23 (p = 0.0319, M-W) presented significant differences between R and HC, with R being higher." (PMID 37896882, 2023). "Pro-inflammatory cytokines (IL-6, IFNγ, TNFα, and IL-12p40) as well as the anti-inflammatory cytokine IL-13 increased, whereas release of IL-1Ra (an IL-1β inhibitor) was reduced by infection with the mutant strain." (PMID 37669276, 2023). "Serum pH1N1-specific IgG levels were also increased in the Ad-HA/NP+Ad-IL-1β group, while pH1N1 infection increased the pH1N1-specific IgA titers." (PMID 37153548, 2023). "Western blotting results showed that IL-1β was indeed detected after infection with HvAV-3h, suggesting that necrosis or pyroptosis occurred after infection with HvAV-3h." (PMID 36744941, 2023). "The results demonstrated that Evans blue, TNF-α and IL-1β levels were significantly increased in the infection groups compared to the control group." (PMID 36341547, 2023). "The NLRP3 inflammasome is a component of the inflammatory response to infection and injury, orchestrating the maturation and release of the pro-inflammatory cytokines interleukin-1β (IL-1β), IL-18, and triggering pyroptotic cell death." (PMID 38129373, 2023). "Activation of the nucleotide-binding domain leucine-rich repeat containing a pyrin domain 3 (NLRP3) inflammasome and IL-1 beta (IL-1β) secretion in immune cells is protective in host defense to infection." (PMID 37914804, 2023). "The infected mice pre-treated with CLE for 2 weeks showed significantly (p < 0.05) increased levels of IFN-γ and IL-1β cytokines on the third day post-infection." (PMID 37249978, 2023).
infection (continued). "Zhou and colleagues first described the activation of the NLRP3 inflammasome in IL-1β secretion in macrophages after infection by C. pseudotuberculosis." (PMID 36761775, 2023). "Consistently, crotonate reduced NLRP3/caspase-1 dependent cleavage of the proinflammatory cytokine interleukin (IL)-1β at 3 and 6 h post-infection." (PMID 37929941, 2023). "Inflammasomes are multimeric protein complexes which assemble in immune cells upon disruption of cellular homeostasis (during infection or injury), and drive the processing and release of pro-inflammatory cytokines IL-1β and IL-18." (PMID 38129373, 2023). "Overall, in this study, we found that Del2R infection induces high levels of IL-1β and TNF-α in vitro and in vivo, and the MGF300-2R plays a critical role in inhibiting the production of inflammatory cytokines." (PMID 37566637, 2023). "Macrophages and supernatants were collected after different times (0h, 4h, 12h, 24h and 48h) of B. abortus-infection, and mRNA expression of macrophage M1 (Tnfα, Nos2 and Il1β) and M2 (Tgfβ, Arg1, Il10) polarization marker genes were detected by RT-qPCR." (PMID 37325614, 2023). "Like H. pylori, infection by Mycoplasma hyorhinis (M. hyorhinis, M. hy) fosters IL-1β secretion, which underpins GC cell migration and invasion, in an NLRP3-dependent manner." (PMID 37891577, 2023). "IL-1β, the major endogenous pyrogen, possessed multiple properties in response to infection, injury, and immune alteration." (PMID 37628768, 2023). "The expression of some inflammatory molecules (IL-1β, IL-6, IL-12, and TNFα) significantly decreased in the siIRF5-treated group, which differed from that in miR-146b deficiency following CFT073 infection." (PMID 37909731, 2023). "Further confirming the therapeutic efficacy of IL-1β blockade post infection, we found improved lung function in Ab-treated mice." (PMID 38077031, 2023). "These two cell types, typically defined by expression of Ly6g (neutrophils) and Adgre1 (F4/80, macrophages), expressed a similar transcriptional program following infection, including S100a8/9, Lcn2, Cxcl1, and Il1b." (PMID 38096412, 2023). "The IL-1β protein level was also upregulated after DUSP1 knockdown during infections by P. aeruginosa, C. diphtheriae, and the HSV-1 ICP34.5 mutant." (PMID 36625590, 2023). "This strain was shown to protect zebrafish larvae against V. anguillarum PF4 infection by preventing the expression of inflammatory cytokines IL1β and TNFα." (PMID 36836388, 2023). "In fact, when mice were infected with S. pneumoniae serotype 1, we observed a strong PTX3 production during the invasive phase of the infection and a correlation with IL-1β levels." (PMID 37222419, 2023). "The Tc/EOW group produced a response with a predominance of IFN-γ and IL-12B, and significantly high IL-1β (p = 0.0152) and IL-10 (p = 0.0247), showing the highest concentration at the time of infection of this last cytokine." (PMID 37242721, 2023). "While Il1β, Il6 and Tnfα show a significantly altered gene expression after infection for both, DMSO and DEVD-fmk treated BV2." (PMID 36906641, 2023). "IL-1β is secreted in response to infection in order to facilitate the recruitment and retention of macrophages." (PMID 36932407, 2023). "The present study suggests the IL-1b potentiality to act protectively for the host towards establishing the virus carrier state (in a long-term infection), a role which needs further elucidation." (PMID 38068937, 2023). "Our data indicate that Il-1b and Mcp1 transcripts can be modulated by infection in the presence of L-arginine and putrescine." (PMID 37000792, 2023). "HBV modulates liver macrophage function to impair the production of IL1B to maintain the infection status." (PMID 36756119, 2023). "Studies have shown increased levels of TNF, IL-1β, 4, 6, 7, 8, 10, and 15 two months after the infection, and increased levels of IL-1β, six and TNF-α eight months later." (PMID 37894116, 2023).